ETS1 (ETS proto-oncogene 1, transcription factor)
Diseases named in the same sentence as ETS1 in open-access papers (continued):
Sharing a sentence is not in itself a finding about the gene and the disease.
squamous cell tumors (1 paper, 2009). "High level expression of the Ets1 oncogene has been linked previously to tumor progression, invasion and metastasis in squamous cell tumors as well as various other tumor types." (PMID 19142229, 2009). "Together, these studies extend our understanding of the role of Ets1 in squamous cell tumors and suggest mechanisms by which Ets1 can promote cellular transformation and tumor progression." (PMID 19142229, 2009).
thymoma (1 paper, 2011). A neoplasm arising from the epithelial cells of the thymus. "However, we could not confirm an effect of miR-133b or miR-206 overexpression on constructs containing the 3′-UTR of the Ets1 gene in the context of the BW5147α-β- thymoma cell line." (PMID 21637854, 2011).
thyroid tumor (1 paper, 2025). A benign or malignant neoplasm affecting the thyroid gland. "Although aberrant ETS1 activation has been documented in various solid tumors, a thorough and systematic analysis elucidating the role of ETS1 in thyroid tumor progression remains limited." (PMID 39941022, 2025).
uterine fibroids (1 paper, 2022). "Compared to the normal ovarian surface epithelium collected from patients with uterine fibroids, ETS1 expression in tumor tissue was found to be higher." (PMID 36477408, 2022).
uveal melanoma (1 paper, 2025). A melanoma derived from melanocytes of the uveal tract. "The STRING analysis performed in plasma samples of uveal melanoma patients for miR-155-5p showed that the molecules with the most interaction of the miR-155-5p were CBL and RAP1B proteins along with FOS and ETS1 (p value: 0.000399)." (PMID 38914847, 2025).
tumor (264 papers, 2002 to 2026). "EFNA4 is involved in various tumour signalling pathways, whereas ETS1 is linked to tumour immunity and is positively correlated with fibroblast-related genes, contributing to chemotherapy resistance in low-purity tumours." (PMID 41162582, 2025). "We constructed a tumour-based risk signature for GC based on EFNA4, ETS1, and marker genes of the tumour cell cluster." (PMID 41162582, 2025). "Aberrant ETS1 expression has been implicated in the progression of numerous malignancies and promotes tumor metastasis." (PMID 40628704, 2025). "Overall, ETS-1 plays a key regulatory role across various tumor types, with its expression and functional activity closely associated with tumor occurrence, development, prognosis, and response to immunotherapy." (PMID 40181983, 2025). "As a multifunctional transcription factor, ETS-1 regulates genes associated with immunosuppression, thereby facilitating tumor immune escape." (PMID 40181983, 2025). "ETS-1 had a far stronger association with VEGF-A in the peritumoral tissue compared to the tumor tissue (rs = 0.32 vs. 0.63)." (PMID 38607072, 2024). "High IGF2, FOXM1 and ETS1 levels also were significantly associated with lymphatic invasion and advanced tumor stage." (PMID 33407516, 2021). "Recently, increasing data have confirmed that the high level of ETS-1 in tumor tissues is associated with the prognosis of patients with malignancies, including breast cancer, lung cancer or liver cancer." (PMID 34123781, 2021). "In gastric mucosa, it has been reported that ETS1 isn’t expressed in the normal GECs; however, ETS1 is upregulated in GC cells, and associated with tumor invasion and metastasis." (PMID 32612120, 2020). "Despite such clear associations, the molecular attributes of ETS1, in particular its target gene repertoire and function in context of a defined tumor subtype remains ill-understood." (PMID 31306413, 2019). "High levels of Ets-1 expression are observed in a wide variety of cancer types including those of the breast, prostate and ovary; this suggests that the association between Ets-1 expression and tumor progression is a generalized phenomena." (PMID 24280356, 2013). "Ets-1 is widely expressed by tumor cells, endothelial cells and tumor-associated fibroblasts, where it is known to contribute to tumor angiogenesis and cancer cell invasion." (PMID 24280356, 2013). "Local administration of a dominant-negative form of Ets-1, encoding the DNA binding domain, significantly blocked tumor angiogenesis and tumor growth." (PMID 20454645, 2010). "The over-expression of Ets-1 has been associated with a multitude of different cancers, specifically with regards to tumour progression and invasion." (PMID 21042593, 2010). "This again supports the concept that increased angiogenesis in Ets-1 expressing tumors is associated with increased tumor progression and a worse prognosis." (PMID 20454645, 2010). "ETS-1 has also been implicated in various pathways involved in tumor angiogenesis through the activation of various target genes." (PMID 18958307, 2008). "Ets-1 and members of Ets family have also been linked to leukemia, tumor progression and metastasis." (PMID 17987123, 2007). "Interestingly, upregulation of FACT and ETS-1 have been linked to oncogenesis and/or tumor invasion." (PMID 40060670, 2025). "ETS1 played a proactive role in angiogenesis, particularly in tumor-associated angiogenesis." (PMID 40496867, 2025). "The up-regulation of Ets-1 expression is intimately linked to tumour invasion and metastasis." (PMID 40181983, 2025). "Notably, ETS1 has been reported to be associated with the immune microenvironment and immune cell function in multiple human tumours." (PMID 41162582, 2025). "Notably, aberrant ETS-1 expression in various malignancies is strongly associated with tumor progression, including angiogenesis, extracellular matrix degradation, and metastasis—crucial steps in cancer invasion." (PMID 40181983, 2025).
tumor (continued). "Furthermore, ETS1 expression is linked to tumor stage in a variety of malignancies, including BRCA, ACC, MESO, KICH, KIRC, STAD, and THCA." (PMID 35463077, 2022). "Moreover, some previous studies indicate that ETS1 impacts tumor growth and immune responses inside TME-associated macrophages." (PMID 35463077, 2022). "Moreover, an increased ETS1 expression has been associated with high tumor grading, poor differentiation, and more pronounced invasiveness – ultimately being considered a marker of poor prognosis." (PMID 34023818, 2021). "Interestingly, the analysis highlighted a number of predicted biological effects due to loss of ETS1, such as tumor cell migration and invasion, cell cycle progression and tumor growth." (PMID 31306413, 2019). "The strong association of ETS1 function with TGF-β induced EMT pathway prompted us to further validate this relationship with an independent gene-signature aimed at quantifying the EMT status of a tumor." (PMID 31306413, 2019). "ETS1 has previously been implicated in tumor progression, immunity, and angiogenesis." (PMID 29738565, 2018). "Increased expression of ETS‐1 is associated with cancer metastasis, and its forced expression leads to a transformed phenotype, as shown by tumor formation in xenograft mice." (PMID 28236660, 2017). "Dysregulated Ets1 expression induced a wide spectrum of progressive premalignant changes such as those induced by chemical carcinogens, activated oncogenes, or loss of tumor suppressors in well-established mouse models of squamous cell carcinogenesis." (PMID 19142229, 2009). "Our observations could also be explained by epigenetic changes in tumor cells having differential effects on the regulation of genes encoding transcription factors and/or cotranscriptional regulators of ETS-1 and ETS-2." (PMID 18958307, 2008). "Since uPA is causally involved in tumour progression, we correlated its levels with those of Ets-1." (PMID 15365563, 2004). "Furthermore, tumor Ets-1 expression is linked to basal-like tumors and poor disease survival." (PMID 22971289, 2012). "Therefore the expression of Ets-1 was significantly associated with the tumor grade." (PMID 20454645, 2010). "Therefore, Ets1 may stimulate transcription of many genes associated with tumor invasion and metastasis, and would be an effective target in preventing invasion of malignant tumors." (PMID 19930697, 2009). "We then performed a thorough study using the TISIDB database to further elucidate immune checkpoint correlations and the relationship between EFNA4, ETS1, and tumour immunity in the context of GC." (PMID 41162582, 2025). "For example, does the function of ETS1 in promoting hEMT depend on specific tumor spatial contexts, such as hypoxic regions?" (PMID 40777467, 2025). "Most notably, the percentage of tumour cells with high ETS1 and low EFNA4 expression was higher in AGC than in EGC." (PMID 41162582, 2025). "For example, ETS1, a key oncogenic TF functioning in tumorigenesis, showed the highest number of recovered known TGs in all tumor datasets across all ranked TGs when analyzed with spMOCA, except for LUSC, where ETS1 was not identified as a TF." (PMID 41370198, 2025). "Our study has elucidated the distinct roles of EFNA4 and ETS1 in GC, as well as their expression patterns in tumour cells at the single-cell level." (PMID 41162582, 2025). "Research has demonstrated that ETS-1 regulates the expression of MHC Class I molecules in tumour cells, thereby influencing the recognition of tumour cells by cytotoxic T cells." (PMID 40181983, 2025). "Beyond metastasis, we uncovered a previously underappreciated role for ETS1 in anti-tumor immune regulation." (PMID 40777467, 2025). "Specifically, we stratified tumor samples into ETS1-high and ETS1-low groups (top and bottom 20%, respectively) based on ETS1 expression levels in cancer cells." (PMID 40777467, 2025).
tumor (continued). "Under pathological conditions, such as in tumor tissues, ETS-1 expression is often abnormally elevated, correlating with its role in tumorigenesis, progression, and metastasis." (PMID 40181983, 2025). "ETS-1 is a proto-oncoprotein and its upregulation promotes cellular transformation and tumor invasion." (PMID 40060670, 2025). "This review highlights the pivotal role of ETS-1 in tumor immunity, detailing its aberrant expression across various tumor types and its significant influence on tumorigenesis, progression, immune evasion, and sensitivity to immunotherapy." (PMID 40181983, 2025). "Collectively, these studies highlight the multifaceted role of ETS-1 in promoting tumour immune evasion and progression by regulating antigen presentation and cytokine networks." (PMID 40181983, 2025). "This review systematically examines the expression and function of ETS-1 within the tumor immune microenvironment, aiming to elucidate its mechanisms in tumor initiation, progression, and metastasis." (PMID 40181983, 2025). "Together, our work reveals ETS1 as a dual driver of tumor distal metastasis and immune evasion in UASCC, while nominating HSP90 inhibition as a tailored treatment strategy for ETS1-driven tumors." (PMID 40777467, 2025). "Given the observed regulation of immune modulators by ETS1, we next investigated the functional consequences of ETS1 overexpression on anti-tumor immune responses in vivo." (PMID 40777467, 2025). "ETS-1 plays a pivotal role in the tumour immune microenvironment by modulating antigen presentation and cytokine networks through multiple mechanisms." (PMID 40181983, 2025). "ETS1 and MYBL2 are associated with angiogenesis regulation, with ETS1 regulating VEGF production, crucial for neovascularization and tumor proliferation." (PMID 39912562, 2025). "Overall, this review aims to provide a comprehensive analysis of ETS-1’s mechanisms in tumor immunity, offering novel theoretical and experimental insights for tumor diagnosis, treatment, and prognosis assessment." (PMID 40181983, 2025). "This suggests a multifaceted regulatory network where ETS1, miR-203a-3p, and miR-204-3p interact with other molecular pathways, potentially leading to enhanced tumor aggressiveness and poor clinical outcomes in PTC patients." (PMID 39941022, 2025). "By sponging tumor-suppressive miRNAs, circPPFIA2 unleashes ETS1-mediated transcriptional programs that fuel proliferation, metastasis, and enzalutamide resistance." (PMID 41360764, 2025). "It has been shown that ETS1 is essential for the BRAFV600E-induced signaling pathway that promotes tumor survival and progression of PTC." (PMID 40722658, 2025). "The MC3Ri tumor consisted primarily of the red subclone, which acquired CDKN2A and ETS1 mutations from the founding clone, possibly correlating with the emergence of the SHM2 clonotype." (PMID 40876452, 2025). "TGF-β signalling promotes ETS-1 expression, influencing the immune response within the tumour microenvironment and the potential for tumour metastasis, thereby supporting the aggressiveness of tumors." (PMID 40181983, 2025). "Unexpectedly, ETS1 also orchestrated an immune-cold tumor microenvironment by transcriptionally activating both STAT1 and PD-L1 (CD274) genes, suppressing T lymphocyte infiltration, and elevating immune checkpoint molecules." (PMID 40777467, 2025). "It is interesting to notice that, if positive, thyroid cells of the follicles close to the tumor showed intense nuclear staining, while the intensity of ETS1 IHC staining of NMT declined along with the distance from the tumor." (PMID 39941022, 2025). "The ECM plays a critical role in tumor growth, invasion, and metastasis, and ETS-1 contributes to ECM remodeling by up-regulating matrix metalloproteinases (MMPs)." (PMID 40181983, 2025).
tumor (continued). "ETS1 appears to play a role in regulating the invasive behavior of many normal and tumor-like cells, as it has been shown that ETS1 is required for adopting an angiogenic, blood vessel-forming phenotype in endothelial cells." (PMID 39941022, 2025). "WTAP has also been reported to be overexpressed in HCC, promoting tumor growth by facilitating m6A of ETS1 mRNA." (PMID 40568348, 2025). "To investigate the functional role of ETS1 in tumor metastasis, we selected two UASCC cell lines, TE5 and TT, with low ETS1 expression and relatively low metastatic potential for gain-of-function studies." (PMID 40777467, 2025). "Our analysis found that ETS1 is co-expressed with STAT1 in immunosuppressive tumor subpopulations and promotes the upregulation of immune checkpoint ligands and T cell exhaustion markers." (PMID 40948762, 2025). "This means that in PTC, lower values of ETS1 in the cytoplasm correlate with a higher pT grade of the tumor, while lower values of ETS1 in the nucleus correlate with the lnm occurrence." (PMID 39941022, 2025). "Such a pathway is in agreement with prior findings wherein HIF1A (possibly induced by tumor hypoxia) amplifies ETS1, which in turn promotes metastatic traits." (PMID 40777467, 2025). "While their mechanisms differ, these inhibitors share a common goal of reducing ETS-1 expression and activity in tumor cells." (PMID 40181983, 2025). "Collectively, these results highlight a regulatory link between ETS1 and STAT1/PD-L1, implicating ETS1 as a potential modulator of key anti-tumor immune regulators." (PMID 40777467, 2025). "This study aims to systematically analyze the role of ETS-1 within the tumor immune microenvironment, elucidating its mechanisms in cancer initiation, progression, and metastasis." (PMID 40181983, 2025). "ETS-1 plays a crucial role in shaping the tumor immune microenvironment by regulating immune cell infiltration, activation, and the expression of immunosuppressive factors." (PMID 40181983, 2025). "Our analysis has revealed a positive correlation between ETS1 and the immune checkpoints PDCD1 and TIGIT, which are linked to immune dysfunction and tumour progression." (PMID 41162582, 2025). "In animal models, ETS-1 inhibitors have demonstrated significant suppression of tumor growth and metastasis, along with enhancement of anti-tumor immune responses." (PMID 40181983, 2025). "To thoroughly understand ETS-1’s role, we compare its expression in various tumor types and adjacent normal tissues." (PMID 40181983, 2025). "The expression of chemoresistance genes has been detected, including KLF4 (doxorubicin and ifosfamide), ULK1, LUM, GPNMB, and CAVIN1 (doxorubicin), and AHNAK2 (gemcitabine) in tumor cells and ETS1 (gemcitabine) in TME." (PMID 39685635, 2024). "PECAM1 expression was also closely associated with ETS1/PLAT and CD274 (PDL1)/IFNGR1, indicating close involvement of tumor angiogenesis with unique proteolysis and tumor immunity." (PMID 38557819, 2024). "ETS-1 displayed stable and identical significant overexpression in both the proangiogenic phenotypes present in the tumor and the peritumoral mucosa." (PMID 38607072, 2024). "For example, some microRNAs, such as miR-193b, and miR-129-5p, can downregulate Ets-1 expression and reduce the migration and invasion capabilities of tumor cells." (PMID 39468027, 2024). "Ets-1 dysregulation leads to an imbalance in the expression of oncogenes and tumor suppressor genes, thereby promoting tumor progression." (PMID 39468027, 2024). "ETS-1 displays stable and identical significant overexpression in both the proangiogenic phenotypes present in tumor and peritumoral mucosa." (PMID 38607072, 2024). "In the UPS TME, T cells expressed the ETS1 and IL2RG genes associated with resistance to gemcitabine and tumor metastasis, respectively." (PMID 39685635, 2024).